LINC01106 (long independently transcribed non-coding RNA 1106)
Synonyms: FLJ38359
Gene: Long non-coding RNA gene on chromosome 2 (110,353,799 to 110,384,528, reverse strand). Ensembl gene ENSG00000175772.
Diseases named in the same sentence as LINC01106 in open-access papers:
LINC01106 is named in the same sentence as 10 diseases in open-access papers, as found by Europe PMC text mining. Sharing a sentence is not in itself a finding about the gene and the disease. The quoted sentences say what the papers report.
colorectal cancer (6 papers, 2020 to 2025). A primary or metastatic malignant neoplasm that affects the colon or rectum. "For example, LINC01106 has been linked to the amplification of colorectal cancer progression by orchestrating a regulatory feedback loop with Gli family members." (PMID 38255219, 2024). "Additionally, LINC01106 has been identified as a promoter of growth and stemness in colorectal cancer by forming a positive feedback loop that controls the Gli family factors." (PMID 38255219, 2024). "LINC01106 has been reported to facilitate proliferation and migration of colorectal cancer cells." (PMID 35581586, 2022). "In colorectal cancer, LINC01106 is highly expressed and enhances proliferation, migration, and stem-like characteristics of colorectal cancer cells via STAT 3 and LINC01106/Gli2 positive feedback loop." (PMID 39735666, 2025). "Further investigation reveals that LINC01106 located in the nuclear could recruit FUS protein to Gli1 and Gli2 promoters, hence activating Gli1 and Gli2 transcription and promoting colorectal cancer formation." (PMID 35581586, 2022).
bladder cancer (3 papers, 2020 to 2025). "LINC01106 is upregulated in lung adenocarcinoma, non-small cell lung cancer, and bladder cancer and functions as a novel diagnostic and prognostic marker in colorectal and gastric adenocarcinomas." (PMID 40969769, 2025). "In the context of bladder cancer, LINC01106 has been found to influence ELK3 and HOXD8 at the post-transcriptional level, thereby accelerating the disease’s advancement." (PMID 38255219, 2024).
colon adenocarcinoma (1 paper, 2022). "LINC01106 is upregulated in colon adenocarcinoma (COAD) tissues (>1.5 fold as compared to normal/adjacent normal tissues) and negatively correlates with overall survival of COAD patients." (PMID 36429127, 2022).
lung carcinoma (1 paper, 2025). "By shedding light on these complex relationships, our research will not only enhance our comprehension of the intricate molecular mechanisms underlying lung cancer but also open up new possibilities for LINC01106 as a potential therapeutic target for LUAD." (PMID 39735666, 2025). "However, a crucial aspect that remains unclear is the involvement of LINC01106 in regulating autophagy and its impact on the progression of lung cancer." (PMID 39735666, 2025).
tumor (4 papers, 2023 to 2025). "Furthermore, immunohistochemical analysis revealed a significant decrease in Ki67 protein expression in mouse tumor tissues derived from sh-LINC01106 injected xenografts, suggesting that LINC01106 deficiency inhibits tumor cell proliferation in vivo." (PMID 39735666, 2025). "KIAA1429 promotes LINC01106 expression through m6A modification, ultimately enhancing tumor cell proliferation, invasion, migration, and xenograft tumor growth in nude mice." (PMID 41190085, 2025). "LncRNA AC005261.1, AC021321.1, AL024508.2, LINC02446 and LINC01106 were lowly expressed in tumor cells, while ARHGAP5-AS1 showed the opposite trend." (PMID 37424068, 2023). "Finally, quantitative RT-PCR showed that AC005261.1, AC021321.1, AL024508.2, LINC02446 and LINC01106 were lowly expressed in tumor cells, while ARHGAP5-AS1 showed the opposite trend." (PMID 37424068, 2023).
cancer (3 papers, 2020 to 2025). A tumor composed of atypical neoplastic, often pleomorphic cells that invade other tissues. "TCGA pan-cancer correlation analysis revealed a significant positive association between METTL3 and LINC01106 in BCa samples." (PMID 38255219, 2024). "While numerous studies have underscored the significance of LINC01106 in different cancers, its multifaceted roles are evident." (PMID 38255219, 2024). "LINC01106 is an oncogenic lncRNA and exhibits an oncogenic function in multiple cancer types." (PMID 39735666, 2025). "In our study, we observed that linc01106 plays a significant role in promoting LUAD development and its silencing had inhibitory effects on cancer development." (PMID 39735666, 2025).
LINC01106 also shares sentences with these, for which no sentence is quoted: colon cancer (1 paper); gastric adenocarcinoma (1); lung adenocarcinoma (1); non-small cell lung carcinoma (1).